ENSG00000275895 (U2 small nuclear RNA auxiliary factor 1-like 5)
Synonyms: U2AF1L5; LOC102724594
Gene: Gene (Ensembl biotype artifact) on chromosome 21 (6,484,623 to 6,499,248, reverse strand). Ensembl gene ENSG00000275895.
Diseases named in the same sentence as ENSG00000275895 in open-access papers:
ENSG00000275895 is named in the same sentence as 1 disease in open-access papers, as found by Europe PMC text mining. Sharing a sentence is not in itself a finding about the gene and the disease.
ENSG00000275895 shares sentences with these, for which no sentence is quoted: Down syndrome (1 paper).